NPFF (neuropeptide FF-amide peptide precursor)
Description:
Morphine modulating peptides. Have wide-ranging physiologic effects, including the modulation of morphine-induced analgesia, elevation of arterial blood pressure, and increased somatostatin secretion from the pancreas. Neuropeptide FF potentiates and sensitizes ASIC1 and ASIC3 channels.
Synonyms: FMRFAL
Tractability: Antibody: its Gene Ontology location is reachable by antibodies, with high confidence; UniProt places it where antibodies can reach, with medium confidence; UniProt predicts a signal peptide or a membrane-spanning region.
Gene: Protein-coding gene on chromosome 12 (53,506,684 to 53,507,491, reverse strand). Ensembl gene ENSG00000139574.
Subcellular location: Secreted
Pathways (Reactome):
Signal Transduction: G alpha (q) signalling events; Orexin and neuropeptides FF and QRFP bind to their respective receptors
Gene Ontology:
Molecular function: neuropeptide activity; neuropeptide hormone activity; signaling receptor binding; G protein-coupled receptor binding
Biological process: neuropeptide signaling pathway; acute inflammatory response to antigenic stimulus; chemical synaptic transmission; excitatory postsynaptic potential; positive regulation of blood pressure; maternal process involved in female pregnancy; negative regulation of appetite; negative regulation of heart rate; negative regulation of insulin secretion; positive regulation of cytosolic calcium ion concentration; regulation of membrane depolarization; response to xenobiotic stimulus; somatostatin secretion; spinal cord development; vasopressin secretion
Cellular component: axon terminus; dendrite; extracellular region; neuronal dense core vesicle; perikaryon; postsynapse; vesicle
Genetic constraint (gnomAD): Loss-of-function variants: 16 observed, 13.71 expected, observed/expected ratio (o/e) 1.17, 90% interval 0.79 to 1.73. The upper end of that interval is the gene's LOEUF score, 1.73, which puts it in group 6 of 6, group 1 being the genes least tolerant of losing a copy. Missense variants: 140 observed, 137.09 expected, observed/expected ratio (o/e) 1.02, 90% interval 0.89 to 1.17. Synonymous variants: 56 observed, 59.54 expected, observed/expected ratio (o/e) 0.94, 90% interval 0.76 to 1.17.
Homologues: Orthologues: chimpanzee NPFF (98% identical), pig NPFF (77% identical), guinea pig NPFF (73% identical), rabbit NPFF (72% identical), rat Npff (65% identical), mouse Npff (61% identical), zebrafish npffl (32% identical).
Diseases named in the same sentence as NPFF in open-access papers:
NPFF is named in the same sentence as 25 diseases in open-access papers, as found by Europe PMC text mining. Sharing a sentence is not in itself a finding about the gene and the disease. The quoted sentences say what the papers report.
Hypertension (5 papers, 2014 to 2025). The presence of chronic increased pressure in the systemic arterial system. "Whether decreased NPFF expression is a cause or consequence of hypertension remains to be addressed, but the present study provides an impetus to examine the role of this peptide in the development of hypertension in animal models of this disease." (PMID 25161813, 2014). "NPFF is a potential target in the treatment of hypertension." (PMID 39769048, 2024). "Neuropeptide FF (NPFF), originally isolated from the bovine brain, has been suggested to contribute to the pathogenesis of hypertension." (PMID 38965251, 2024).
Obesity (4 papers, 2019 to 2022). Accumulation of substantial excess body fat. "ATMs express NPFFR2, a receptor for the appetite-reducing neuropeptide FF (NPFF), whose plasma levels decrease in obesity, and NPFFR2 deficiency in ATMs abolished both M2 activation and ATM proliferation." (PMID 32646451, 2020). "Collectively, our study reveals the effect of NPFF on ARC NPY neuron activity in a human-based system, indicating the potential of targeting NPFFR2 for anti-obesity therapies." (PMID 35328681, 2022). "Additionally, such a model would allow researchers to perform studies on signaling mechanisms of NPFF to gain new insights into the nature of anorexigenic effects of NPFFR2 and to evaluate the therapeutic potential of NPFFR2 as an anti-obesity target." (PMID 35328681, 2022). "The role of NPFF and NPFF2R have been much less explored in the context of obesity." (PMID 35105898, 2022). "Accordingly, the spotted sea bass NPFF peptide may act in both central and peripheral tissues to increase food intake and play a negative role in lipid metabolism and obesity regulation by binding to Npffrs." (PMID 31447787, 2019).
migraine (3 papers, 2020 to 2024). "Neuropeptide FF (NPFF) has recently been identified in a genome-wide association study as a candidate risk factor for migraine, with the top migraine-associated single nucleotide polymorphism in the NPFF gene locus (12q13.13) being rs11170566." (PMID 32640973, 2020). "On the other hand, Neuropeptide FF (NPFF) is a candidate transmitter/modulator for migraine, and stimulation of its receptor, NPFFR2, increases the expression and release of CGRP in mice sensory neurons." (PMID 32640973, 2020).
Anxiety (1 paper, 2017). Intense feelings of nervousness, tension, or panic often arise in response to interpersonal stresses. "Treatment with RF9 reverses amphetamine withdrawal-induced anxiety-like behavior, and dansyl-PQRamide (a putative NPFF antagonist) reduces anxiety responses triggered by ethanol withdrawal." (PMID 28825666, 2017). "However, little is known about the action of NPFF on HPA axis activity and anxiety-like behaviors, and the role of the individual receptors remains unclear." (PMID 28825666, 2017).
bacterial pneumonia (1 paper, 2025). Acute infection of the lung parenchyma caused by bacteria (e.g., Streptococcus pneumoniae, Haemophilus influenzae, Chlamydia pneumoniae, Mycoplasma pneumoniae, and Legionella pneumophila). "Research has revealed that Mas‐related of GPCR a1 (Mrgpra1) are associated with neuropeptide FF (NPFF), which have the ability to direct neutrophil specialization in cases of bacterial pneumonia." (PMID 40260014, 2025).
dependence (1 paper, 2020). "The involvement of neuropeptide FF (NPFF) in modulation of pain perception, opioid-induced tolerance and dependence was well documented in contrast to respiratory depression." (PMID 33255594, 2020).
diabetes (1 paper, 2025). "Based on these observations, the increased expression of the gene and protein of NPFF and its receptors in the hypothalamus following exercise in diabetic individuals may represent a proposed mechanism for reducing diabetes-related complications, including weight loss." (PMID 40666184, 2025). "Browning of white adipose tissue (WAT) as a therapeutic target for diabetes seems to be induced by exercise through neuropeptide FF (NPFF) signaling in the hypothalamus and adipose tissue." (PMID 40666184, 2025). "In this study, we aimed to demonstrate that exercise can prevent diabetes and its complications by affecting the hypothalamus role or by increasing the browning of WAT through changes in the gene and protein expression of NPFF and its receptors, either centrally or peripherally." (PMID 40666184, 2025).
respiratory depression (1 paper, 2020). A decrease in ventilation secondary to impaired signals from the central nervous system. "Our finding has uncovered a novel role for NPFF and its receptors and provided a potential new target for reversal of opioid-induced respiratory depression." (PMID 33255594, 2020).
Stroke (1 paper, 2024). Sudden impairment of blood flow to a part of the brain due to occlusion or rupture of an artery to the brain. "Having identified NPFF as a potential contributor to motor function recovery post-stroke, we proceeded to investigate its neuroprotective effects in vitro." (PMID 39519132, 2024). "In addition, although a direct link between NPFF and essential neuroplasticity and synaptic repair pathways in functional recovery after stroke has not been studied, NPFF may have the potential to influence these pathways." (PMID 39519132, 2024).
withdrawal syndrome (1 paper, 2020). "NPFF also seems to play a role in opiate tolerance, since it has been observed that anti-NPFF antibodies can reverse the development of tolerance to morphine, as well as reduce the symptoms of naloxone-induced withdrawal syndrome." (PMID 32998249, 2020).
cancer (1 paper, 2022). A tumor composed of atypical neoplastic, often pleomorphic cells that invade other tissues. "To elucidate the mechanism by which NPFFR2 increases cancer malignancy, we analyzed the expression of representative downstream signaling proteins activated by GPCR signaling in NPFFR2–depleted or NPFF–treated cells." (PMID 36497331, 2022). "Since NPFF and NPFFR2 are not mutually exclusive, there is a difference in the degree of their effect on cancer cells and in signal transduction." (PMID 36497331, 2022).
infection (1 paper, 2024). The state of being infected such as from the introduction of a foreign agent such as serum, vaccine, antigenic substance or organism. "Next, we explored NPFF+ cells in vivo, and found that after infection, neutrophils were the predominant source of NPFF+ in the lungs." (PMID 38295799, 2024).
NPFF also shares sentences with these, for which no sentence is quoted: cognitive deficits (2 papers); Apnea (1); cognitive decline (1); depression (1); essential hypertension (1); glioblastoma (1); hypothyroidism (1); injury (1); metabolic disease (1); neuroblastoma (1); neurological disorders (1); spinal cord injury (1); tumour (1).